MAPK13 (mitogen-activated protein kinase 13)
Description:
Serine/threonine kinase which acts as an essential component of the MAP kinase signal transduction pathway. MAPK13 is one of the four p38 MAPKs which play an important role in the cascades of cellular responses evoked by extracellular stimuli such as pro-inflammatory cytokines or physical stress leading to direct activation of transcription factors such as ELK1 and ATF2. Accordingly, p38 MAPKs phosphorylate a broad range of proteins and it has been estimated that they may have approximately 200 to 300 substrates each. MAPK13 is one of the less studied p38 MAPK isoforms. Some of the targets are downstream kinases such as MAPKAPK2, which are activated through phosphorylation and further phosphorylate additional targets. Plays a role in the regulation of protein translation by phosphorylating and inactivating EEF2K. Involved in cytoskeletal remodeling through phosphorylation of MAPT and STMN1. Mediates UV irradiation induced up-regulation of the gene expression of CXCL14. Plays an important role in the regulation of epidermal keratinocyte differentiation, apoptosis and skin tumor development. Phosphorylates the transcriptional activator MYB in response to stress which leads to rapid MYB degradation via a proteasome-dependent pathway. MAPK13 also phosphorylates and down-regulates PRKD1 during regulation of insulin secretion in pancreatic beta cells.
Synonyms: MAPK 13; PRKM13; SAPK4; p38delta; MAPK-13
Tractability: Small molecule: a structure with a bound ligand is known; a high-quality ligand is known; it has a high-quality binding pocket; it belongs to a druggable protein family. PROTAC: it is named in the literature on targeted protein degradation; ubiquitination databases record sites on it; its protein half-life has been measured; a small molecule that binds it is known.
Target class: Protein Kinase; CMGC protein kinase group; CMGC protein kinase p38 subfamily; CMGC protein kinase MAPK family; Enzyme; Kinase
Chemical probes: DORAMAPIMOD (high quality)
Gene: Protein-coding gene on chromosome 6 (36,127,809 to 36,144,524, forward strand). Ensembl gene ENSG00000156711.
Subcellular location (Human Protein Atlas): Cytosol; Nucleoli; Nucleoli rim; Nucleoplasm
Pathways (Reactome):
Signal Transduction: VEGFA-VEGFR2 Pathway; p38MAPK events
Immune System: NOD1/2 Signaling Pathway
Gene Ontology:
Molecular function: MAP kinase activity; protein binding; protein serine/threonine kinase activity; ATP binding; protein kinase activity; protein serine kinase activity
Biological process: cellular response to anisomycin; cellular response to hydrogen peroxide; cellular response to interleukin-1; cellular response to sodium arsenite; cellular response to sorbitol; cellular response to UV; positive regulation of inflammatory response; positive regulation of interleukin-6 production; response to osmotic stress; stress-activated MAPK cascade; intracellular signal transduction; cellular response to stress; MAPK cascade
Cellular component: cytosol
Genetic constraint (gnomAD): Loss-of-function variants: 35 observed, 51.24 expected, observed/expected ratio (o/e) 0.68, 90% interval 0.52 to 0.91. The upper end of that interval is the gene's LOEUF score, 0.91, which puts it in group 3 of 6, group 1 being the genes least tolerant of losing a copy. Missense variants: 435 observed, 451.36 expected, observed/expected ratio (o/e) 0.96, 90% interval 0.89 to 1.04. Synonymous variants: 166 observed, 181.89 expected, observed/expected ratio (o/e) 0.91, 90% interval 0.8 to 1.04.
Homologues: Orthologues: pig MAPK13 (95% identical), dog MAPK13 (94% identical), chimpanzee MAPK13 (94% identical), mouse Mapk13 (93% identical), macaque MAPK13 (93% identical), rat Mapk13 (93% identical), guinea pig MAPK13 (93% identical), tropical clawed frog mapk13 (74% identical), rabbit MAPK13 (73% identical), zebrafish mapk13 (65% identical), Caenorhabditis elegans pmk-1 (53% identical), Caenorhabditis elegans pmk-2 (50% identical), and 12 more. Paralogues in human: MAPK12 (65% identical), MAPK14 (59% identical), MAPK11 (58% identical), MAPK10 (46% identical), MAPK8 (46% identical), MAPK9 (45% identical), MAPK3 (41% identical), MAPK1 (41% identical), MAPK7 (39% identical), MAPK15 (36% identical), MAPK6 (35% identical), NLK (34% identical), and 7 more.
Diseases named in the same sentence as MAPK13 in open-access papers:
MAPK13 is named in the same sentence as 52 diseases in open-access papers, as found by Europe PMC text mining. Sharing a sentence is not in itself a finding about the gene and the disease. The quoted sentences say what the papers report.
melanoma (5 papers, 2014 to 2022). A malignant, usually aggressive tumor composed of atypical, neoplastic melanocytes. "Approximately 67% of primary melanoma and 85% of metastatic melanoma presented promoter methylation of the MAPK13 gene, associated with downregulation of p38δ mRNA and protein expression." (PMID 33923030, 2021). "Re-expression of p38δ in melanoma cells with MAPK13 promoter methylation reduced proliferation, indicating that p38δ may act as a tumor suppressor in melanoma cell lines." (PMID 33923030, 2021). "Importantly, reestablishment of p38δ MAPK expression in melanoma cells with MAPK13 hypermethylation suppresses cell proliferation." (PMID 25313309, 2014). "Furthermore, treatment of melanoma cells with the demethylating agent 5-aza-2′-deoxycytidine significantly increases the expression of the MAPK13 gene." (PMID 25313309, 2014). "For example, p38δ has been shown to be silenced in malignant melanoma and cutaneous squamous cell carcinoma of the esophagus according to its tumor suppressor role, whereby its expression is eliminated by a mechanism of methylation modification and transcriptional downregulation of its MAPK13 gene." (PMID 35008796, 2021). "The highest correlations observed with HMOX-1 in patients with melanoma were with FZD2 (rho = 0.54), KEAP1 (rho = 0.59), MAPK13 (rho = 0.68), the “ferroptosis” gene FTL (rho = 0.58), and CHUK (rho = −0.50)." (PMID 35053476, 2022). "The observation of the bona fide TSGs affected by promoter hypermethylation in CMM suggests that these molecules, e.g., TCF21, SOCS, RUNX, RASSF6, RASSFA, RARβ, MAPK13, H- and E-cadherin and AGTR, are a candidate for the design of new therapeutic strategies for human melanoma." (PMID 34639015, 2021). "Melanoma cell lines displaying MAPK13 gene promoter methylation do not express significant levels of p38δ MAPK when compared to fibroblasts, melanocytes, and melanoma cell lines with unmethylated MAPK13 promoters." (PMID 25313309, 2014).
asthma (4 papers, 2021 to 2025). "Among the genes involved in these important signaling pathways, HSPA1A, PIK3CG and PIK3R6 seemed to be associated with moderate asthma, while MAPK13 and MMP9 appeared to be associated with severe asthma." (PMID 39088141, 2024). "Recent systems biology analyses identified four potential molecular triggers—AKT1, MAPK13, STAT1, and TLR4—as candidate regulators of asthma-associated signaling pathways." (PMID 40650018, 2025). "The expression of HSPA1A, PIK3CG and PIK3R6 was associated with moderate asthma, while MAPK13 and MMP9 were associated with severe asthma." (PMID 39088141, 2024). "Here, we have analyzed theoretical signaling pathways related to four asthma trigger proteins, AKT1, MAPK13, STAT1, and TLR4, defined by previous systems biology study as proteins able to modify the activation of many effector proteins of respiratory diseases." (PMID 40650018, 2025). "Gene and protein expression of the four potential asthma triggers, AKT1, MAPK13, STAT1, and TLR4, was analyzed in PBMC samples obtained from AA, NA, and HC." (PMID 40650018, 2025). "The expression of HSPA1A, PIK3CG and PIK3R6 in the same 10 and 4 pathways was then verified, while the expression of MAPK13 and MMP9 related to severe asthma was also confirmed." (PMID 39088141, 2024). "MAPK13 demonstrates pro-inflammatory effects in a model of post-viral lung disease but has not been thoroughly studied in asthma models." (PMID 41516283, 2025). "In conclusion, this study supports the potential involvement of AKT1, MAPK13, STAT1, and TLR4 in asthma pathogenesis and highlights differences between allergic and nonallergic asthma at the molecular level." (PMID 40650018, 2025).
cholangiocarcinoma (3 papers, 2014 to 2017). A carcinoma that arises from the intrahepatic biliary tree (intrahepatic cholangiocarcinoma) or from the junction, or adjacent to the junction, of the right and left hepatic ducts (hilar cholangiocarcinoma). "MAPK13 is also involved in cell motility and invasion, serving as a diagnostic marker for cholangiocarcinoma." (PMID 28893210, 2017). "MAPK13 mainly participates in cholangiocarcinoma and increases cell migration; it may play a similar role in CTEPH." (PMID 24337368, 2014). "MAPK13 is a component of the mitogen-activated protein (MAP) kinase family and plays an important role in the development of cancer, such as cholangiocarcinoma." (PMID 28009993, 2017).
endometrial carcinoma (3 papers, 2020 to 2023). A malignant tumor arising from the epithelium that lines the cavity of the uterine body. "Mechanically, circTNFRSF21 acts as a sponge of miR-1227 to rescue MAPK13/ATF2 signaling pathway activity in endometrial cancer cells." (PMID 34552882, 2021).
gynecological cancer (3 papers, 2017 to 2025). "MAPK13 is highly expressed in uterine and ovary tumor tissues, especially in gynecological cancer stem cells, and has tumor-initiating activity that was involved in tumorigenesis." (PMID 28893210, 2017). "In humans, MAPK13 has a potential role in the regulation of gonadotropins and gynecological cancer." (PMID 41300775, 2025). "For example, mitogen-activated protein kinase 13 (MAPK13) is an important part of MAP kinase signaling pathway, which is previously reported to be overexpressed in gynecological cancer stem cells including ovarian cancer compared with adjacent normal tissues." (PMID 36561981, 2022).
breast carcinoma (2 papers, 2022 to 2023). "qPCR analysis further validated MAPK13 induction upon rapamycin treatment in several mTORC1-overactive cells including UMB1949, MCF7 (PI3K-mutated breast cancer), and BT549 (PTEN-deficient breast cancer)." (PMID 37599001, 2023).
colon cancer (2 papers, 2022). "With the exception of SFN and MAPK13, all other genes were upregulated in colon cancer primary tumors compared with normal colon tissue and/or in colon cancer metastases compared with the primary tumor." (PMID 35565214, 2022).
diabetes (2 papers, 2022 to 2024). "In light of the role of MAPK signal pathways in apoptosis, we prove the potential involvement of lncRNA H19/miR-29c/MAPK13 signal pathway in the process of cardiomyocyte apoptosis in diabetes." (PMID 35890121, 2022).
Insulin resistance (2 papers, 2013 to 2024). Increased resistance towards insulin, that is, diminished effectiveness of insulin in reducing blood glucose levels. "MAPK13 null mice exhibit improved glucose tolerance due to enhanced insulin secretion from pancreatic β cells and are protected against high-fat-feeding-induced insulin resistance and oxidative stress-mediated β cell failure." (PMID 23844045, 2013). "The lack of MAPK13 protected against insulin resistance and pancreatic beta cell failure in mice." (PMID 39541108, 2024).
lung adenocarcinoma (2 papers, 2020 to 2024). A carcinoma that arises from the lung and is characterized by the presence of malignant glandular epithelial cells. "As expected, EGFR, ITGA2, KRAS, MMP9, NRAS and MAPK13 had higher levels in lung adenocarcinoma than in normal lung tissues." (PMID 32210363, 2020).
metastatic melanoma (2 papers, 2017 to 2020). A melanoma that has spread from its primary site to another anatomic site. "The most frequently hypermethylated genes identified were HOXA9, C1orf106, HIST1H3E, MAPK13, and LEP, with MAPK13 methylation in 67% of primary and 85% of metastatic melanomas." (PMID 28396701, 2017).
virus infection (2 papers, 2014 to 2023). "We first screened the four p38 isoforms (p38ɑ/MAPK14, p38β/MAPK11, p38γ/MAPK12, and p38δ/MAPK13) as functional differences between the isoforms in the context of virus infection are particularly understudied." (PMID 37345956, 2023).
allergic asthma (1 paper, 2021). A asthma with a basis in a pathological type I hypersensitivity reaction. "The triggering analysis performed on non-allergic asthma revealed that MAPK13 presents the highest individual triggering probability." (PMID 33936056, 2021). "Results of the triggering analysis performed over allergic asthma revealed that STAT1, MAPK13, and TLR4 are the top genes that play a trigger role according to the individual score." (PMID 33936056, 2021). "When looking at the cumulative score, the same combination of proteins (AKT1, STAT1, MAPK13, and TLR4) triggered 89.27% of the non-allergic asthma effector proteins and inclusion of the rest of proteins of interest would not substantially increase this percentage." (PMID 33936056, 2021).
Allergy (1 paper, 2021). An allergy is an immune response or reaction to substances that are usually not harmful. "Therefore, the most promising protein combination as allergy triggers would be formed by AKT1, MAPK13, and STAT1 proteins." (PMID 33936056, 2021).
amyotrophic lateral sclerosis (1 paper, 2015). Amyotrophic lateral sclerosis (ALS) is a neurodegenerative disease characterized by progressive muscular paralysis reflecting degeneration of motor neurons in the primary motor cortex, corticospinal tracts, brainstem and spinal cord. "NF-L binds to Mapk12 (mitogen-activated protein kinase 12), Mapk13, Mapk14, Nefh (neurofilament), Nefm, Prph (peripherin) and Prph2 which are involved in pathway associated to Amyotrophic Lateral Sclerosis (ALS)." (PMID 25561935, 2015).
atherosclerosis (1 paper, 2022). A disease characterized by the build-up of fatty material and calcium deposition in the arterial wall resulting in partial or complete occlusion of the arterial lumen. "Our previous articles reported that the MAPK signaling pathway was related to cardiovascular diseases such as atherosclerosis; therefore, we chose MAPK13 as the target." (PMID 35890121, 2022).
colitis (1 paper, 2022). Inflammation of the colon. "Consistently, MAPK13 plays a pro-oncogenic role in colitis-associated CRC." (PMID 34998382, 2022).
diabetic foot ulcers (1 paper, 2025). "Since these mediators play a critical role in wound healing, they may be an attractive target in diabetic foot ulcers to promote healing by increasing MAPK13 and decreasing TSP1 and CXCR2 in chronic nonhealing wounds." (PMID 41514867, 2025).
Hepatic steatosis (1 paper, 2025). Steatosis is a term used to denote lipid accumulation within hepatocytes. "In summary, our data indicate that KD feeding induces fibrosis and MASH through upregulated Il-6, Tnf, and Mapk13 pathways at TN, whereas adipocyte-specific gp130 deletion prevents KD-induced hepatic steatosis through reduced p-HSL, p-JNK, and p-p38 MAPK signaling." (PMID 40864559, 2025). "Our findings demonstrate that inflammatory and metabolic stress pathways, including TNF, IL-6, IL-1β, and MAPK13 signaling, promote the progression of hepatic steatosis to MASH and fibrosis under KD at TN but not at RT." (PMID 40864559, 2025).
Hyperglycemia (1 paper, 2025). An increased concentration of glucose in the blood. "Overall, the results of this study suggest that hyperglycemia modulates the expression of MAPK13, TSP1, and CXCR2." (PMID 41514867, 2025). "Normally, hyperglycemia increases the expression of MAPK13, and this notion is supported by our immunofluorescence and in vitro PCR findings of increased MAPK13 in fibroblasts expressing p38δ with hyperglycemia." (PMID 41514867, 2025). "This study aims to investigate the effects of hyperglycemia on the expression of MAPK13, CXCR2, and TSP-1." (PMID 41514867, 2025). "In vitro studies showed that hyperglycemia increases the protein expression of MAPK13, TSP1, and CXCR2 at 24 h in rat fibroblasts compared to control cells, as evidenced by increased fluorescence." (PMID 41514867, 2025). "Study limitations and future direction: This study highlights the role of hyperglycemia in modulating the gene and protein expression of MAPK13, TSP1, and CXCR2." (PMID 41514867, 2025). "The results of this study indicate the effects of hyperglycemia on the gene and protein expression of MAPK13, TSP1, and CXCR2, the mediators with a critical role in wound healing." (PMID 41514867, 2025). "Furthermore, in diabetic conditions, hyperglycemia enhances MAPK13 activation, which increases TSP1 expression, further amplifying anti-angiogenic and profibrotic signaling that impairs wound healing and promotes DFU formation." (PMID 41514867, 2025). "The results suggest that hyperglycemia increases the expression of TSP1 and CXCR2, and the effects on MAPK13 are context-dependent." (PMID 41514867, 2025). "The results revealed an increased MAPK13, TSP1, and CXCR2 with hyperglycemia." (PMID 41514867, 2025).
ischemia (1 paper, 2023). A hypoperfusion of the BLOOD through an organ or tissue caused by a PATHOLOGIC CONSTRICTION or obstruction of its BLOOD VESSELS, or an absence of BLOOD CIRCULATION. "In intestinal ischemia–reperfusion (II/R) injury, miR-351-5p was shown to target MAPK13 and sirtuin-6, activate the Bcl2-1/NF-κB signaling pathway and cleave caspase-3, which promotes cell death." (PMID 37686375, 2023).
kidney tumor (1 paper, 2023). "Rapamycin did not induce Mapk13 expression in TSC2-deficient mouse kidney tumor cell lines, indicating the lack of mTORC1 and m6A-dependent MAPK13 regulation mechanisms in mice." (PMID 37599001, 2023).
liver fibrosis (1 paper, 2025). "Similarly, we observed that Mapk13 knockout mice exhibited much lower levels of ALT and AST in serum, less liver fibrosis area and fewer dead cells in liver tissues in DDC-treated mice." (PMID 39962071, 2025).
psoriasis (1 paper, 2021). An autoimmune condition characterized by red, well-delineated plaques with silvery scales that are usually on the extensor surfaces and scalp. "Therefore, consistent with the discussion we propose that MAPKs (MAPK13 and MAPK14) and genes for AP-1 (FOSL1 and FOS) identified from sensitivity analysis of psoriasis are significant genes that might lead psoriasis towards cancer." (PMID 34267747, 2021).
rectal cancer (1 paper, 2022). A primary or metastatic malignant neoplasm that affects the rectum. "We took the intersection of the candidate target genes in the MAPK pathway and the overexpressed genes in colon and rectal cancer in TCGA and GTEx and obtained MAPK13, which was at the core in the MAPK pathway and clearly elevated in CRC." (PMID 34998382, 2022). "MAPK13 was significantly overexpressed in colon and rectal cancer." (PMID 34998382, 2022). "The intersection of the candidate target genes in the MAPK pathway and the overexpressed genes in colon and rectal cancer in TCGA and GTEx was taken, and 5 candidate genes EFNA2, RPS6KA2, MAPK13, EFNA3 and FGFR3 were identified." (PMID 34998382, 2022).
respiratory allergy (1 paper, 2021). "According to the individual score, neither AKT1, MAPK13, nor STAT1 presented a high probability of promoting respiratory allergy on their own." (PMID 33936056, 2021).
squamous cell carcinoma (1 paper, 2025). A carcinoma arising from squamous epithelial cells. "Studies have confirmed that MAPK13 promotes the over-proliferation of epidermal cells and tumorigenesis by inhibiting the expression of proinflammatory cytokines and chemokines in the development of squamous cell carcinoma." (PMID 41331166, 2025).
steatosis (1 paper, 2025). Increased lipid within the cytoplasm of cells. "Therefore, the upregulation of Il-6, Tnf, Mapk13, and Col1a1 pathways under KD at TN likely drives steatosis progression to MASH and fibrosis." (PMID 40864559, 2025).